TNF (tumor necrosis factor)
Diseases named in the same sentence as TNF in open-access papers (continued):
Sharing a sentence is not in itself a finding about the gene and the disease.
thrombosis (71 papers, 2007 to 2026). "Clinical doctors should assess individual thrombosis risk and closely monitor coagulation related indicators when using TNF - α inhibitors." (PMID 40351429, 2025). "When evaluating mono-target therapies, we found over-expressing TNF-α, instead of blocking it, was associated with a decreased activation of Ang2 and Thrombosis, which can be related to decreased organ dysfunctions." (PMID 36261775, 2022). "Tumor necrosis factor-α inhibitors have also been investigated for the treatment of BD-associated thrombosis." (PMID 36530905, 2022). "Positive signals associated with thrombosis at the PT level of five TNF - α blockers." (PMID 40351429, 2025). "Administration of anti-tumor necrosis factor (TNF) monoclonal antibodies with anticoagulation could be considered for treating patients with refractory venous thrombosis who are at low risk of bleeding." (PMID 34154640, 2021). "Lowering Hcyby selected vitamin supplements or TNF blockade may be the futuredirection of prevention from developing the risk of thrombosis and vasculitisof different organ systems and thereby activation of BD disease." (PMID 19197380, 2008). "Trans-endothelial migration of MNC was enhanced in HL, FL and DLBCL with thrombosis and reduced by inflammatory cytokine tumor necrosis factor alpha (TNF-α) that promoted platelet aggregation like interleukin-6 (IL-6) in HL and FL." (PMID 42041535, 2026). "Levels of circulating IL-6 and TNF- α were significantly higher in the thrombosis cohort compared to the non-thrombosis cohort (55 vs. 38, p < 0.02) and (159 vs. 110, p < 0.02) respectively." (PMID 40776916, 2025). "(N = 165,765) Thrombosis-related adverse event signals were detected in all five types of TNF-α inhibitor drugs." (PMID 40351429, 2025). "Numerically, there were 15 allograft failures in the anti-TNFα group (17.2%, of whom 13/15 were complete thrombosis) and 32 in the SOC group (21.5%, of whom 19/32 were complete thrombosis) at 3 years." (PMID 40170787, 2025). "In the present investigation, we found that OP effectively suppressed the activation of TLR4/NF-κB and reduced the levels of inflammatory markers such as TNF-α, IL-1β and IL-6 in liver and lung tissues of mice with carrageenan-induced thrombosis." (PMID 40276603, 2025). "Inflammatory mediators, such as CRP, interleukins (IL-6 and IL-8), and tumor necrosis factor-alpha (TNF-α), play significant roles in both arterial and venous thrombosis." (PMID 39742171, 2024). "Three patients with venous thrombosis were treated with glucocorticoid pulses combined with TNF-α inhibitors, and one patient was treated with IL-6 inhibitors." (PMID 38243321, 2024). "In the current study, αan ideal therapeutic effect was made with anti-TNF-α agents achieved for BD accompanied by pulmonary artery aneurysm and venous thrombosis, and the long-term prognosis should be discussed in further studies." (PMID 38243321, 2024). "Nosaka, M. found that the TNF-α/TNF-Rp55 signal axis can regulate the dissolution of venous thrombosis." (PMID 36717769, 2023). "Enhanced secretion of TNFα promotes apoptosis of the trophoblast and suppresses its invasion, and its elevated local concentrations induce thrombosis and placental ischemia." (PMID 37511039, 2023). "In our previous study, high expression of inflammatory factor TNFα was accompanied by significant downregulation of TGFβ2 within the venous wall after thrombosis." (PMID 35808901, 2022). "In particular, IL-6 seems to play a critical role in inflammation-related thrombosis, together with tumor necrosis factor-alpha (TNFα), interleukin 8 (IL-8), and C-reactive protein (CRP), representing powerful risk predictors for DVT." (PMID 35625609, 2022). "In our previous studies, the expression of the TNFα signalling pathway in the superficial vein wall after thrombosis apparently increased; however, the TGFβ signalling pathway was suppressed." (PMID 35808901, 2022).
thrombosis (continued). "Raised adipocyte generation of PAI-1, MCP-1, and TNF-α is important in the pathogenesis of thrombosis, and IR." (PMID 33639960, 2021). "In addition, to distinguish the potential confounding effects of TNF - α inhibitors and the disease itself on thrombosis, we systematically retrieved clinical study data from healthy subjects." (PMID 40351429, 2025). "It has been suggested that TNF-α, in combination with hormones, contributes to placental thrombosis, which may result in miscarriage; TNF-α levels rise at the onset of labor and during spontaneous abortion." (PMID 40141672, 2025). "DIC is an illness caused by an uncontrollable systemic activation of the clotting cascade due to pro-inflammatory cytokines, such as IL-1β, IL-6, and TNF-α, followed by excessive consumption of clotting factors, microvascular thrombosis, and finally, thrombotic or hemorrhagic episodes." (PMID 38254870, 2024). "This may be because ICIs immunize atherosclerotic T cells through the regulation of T-cell activation, leading to increased interferon-gamma and tumor necrosis factor (TNF)-alpha levels, thereby increasing the risk of coronary thrombosis." (PMID 36742069, 2023). "Moreover, it was shown that pro-inflammatory cytokines (i.e., TNF-α) favor the activation of platelets, leading to the onset of thrombosis and cardiometabolic diseases." (PMID 37763741, 2023). "TNF-α is one of the critical factors in many diseases complicated with venous thrombosis." (PMID 37008026, 2023). "Previous studies confirmed that the TNF-α content continued to rise after thrombosis." (PMID 37008026, 2023). "In our simulations, long term over-expression of TNF-α was likely to decrease the activation of node Thrombosis, which might be a result of its beneficial role in thrombus resolution as indicated in the animal study." (PMID 36261775, 2022). "Furthermore, procyanidin-rich fractions have been found to downregulate the release of pro-inflammatory cytokines, including IL-8, IL-6, and TNF-α, in a rat model of deep vein thrombosis." (PMID 35630834, 2022). "Thrombosis induces the release of cytokines including IL-6, tissue factor, and TNF-α by activating endothelial cells, and inflammation accelerates hypercoagulability state and leads to endothelial damage and platelet aggregation, thus further aggravating the development of DVT." (PMID 32441737, 2020). "However, a study based on 11,881 patients treated with TNF blockers presented a different outcome, namely, that the risk of thrombosis did not increase when patients were exposed to the factor of TNF-α blockers." (PMID 40351429, 2025). "In such a situation, a large amount of cytokines and chemokines are secreted, for example TNF-α, IL-1, IL-6, IL-8, which stimulate other cells of the immune system and the formation of a large inflammation focus, and, as a result, micro- and macro-vascular thrombosis leading to organ failure." (PMID 35328208, 2022). "Similarly, in vivo, the plasma IL-17B, IL-6, and TNF-α were significantly increased after thrombosis in WT mice, and the plasma IL-6 and TNF-α was increased more significantly after the intervention of IL-17B protein on the basis of ligation of IVC (all P < 0.05)." (PMID 36046722, 2022). "TNF interferes with the anticoagulant system and may induce placental thrombosis." (PMID 22110537, 2012). "Recent research has shown that C29 markedly decreases the expression of inflammatory markers, including IL-6 and TNF-α, through the inhibition of the TLR2/NF-κB/COX-2 signaling pathway, which helps relieve traumatic deep vein thrombosis." (PMID 40510367, 2025). "Therefore, anti‐TNF may also mitigate COVID‐19‐induced thrombosis." (PMID 37382255, 2023). "Internleukin-6 (IL-6), IL-8 and tumor necrosis factor alpha (TNF-α) released by the inflammatory cells present in the atherosclerotic plaques are also found to be elevated in patients with venous thrombosis." (PMID 24498202, 2014).
thrombosis (continued). "DEP also significantly increased plasma C-reactive protein (CRP) and TNF α concentrations, systolic blood pressure (SBP) as well as the pial arteriolar thrombosis." (PMID 22745783, 2012). "When stratified by control, non-thrombosis, and thrombosis groups, IL-6 and TNF-α demonstrated a progressive increase across categories, consistent with a graded inflammatory response." (PMID 40776916, 2025). "Increased activity in the NF-KB inflammatory pathway leads to an increase in the secretion of ILs 1, 6, and 8, tumor necrosis factor (TNF) alpha, intracellular adhesion molecule-1 (ICAM-1), and vascular cell adhesion molecule (VCAM), ultimately resulting in a higher incidence of thrombosis." (PMID 40688196, 2025). "Results of the present study demonstrate that G-CSF supplement on iron loading hearts can recruit neutrophils/monocytes and up-regulate tissue factors, ICAM-1, TNF-alpha, and MCP-1 thus further activating inflammatory processes in the endo-myocardium and induce cardiac thrombosis." (PMID 21496220, 2011). "The thrombosis cohort exhibited significantly higher values of pro-inflammatory markers IL-6 [55 pg./mL vs. 38 pg./mL, p < 0.02] and TNF-α [159 pg./mL vs. 110 pg./mL, p < 0.02] compared to the non-event cohort, suggesting an increased risk of developing a thrombus in the former." (PMID 40776916, 2025). "Regarding DLBCL patients’ daily living abilities, the ECOG Scale of Performance Status (ECOG PS) was in negative correlation with IL-8 in patients without thrombosis and with Fibrinogen (ρ = −0.468), TNF-α (ρ = −0.624) and P-selectin (ρ = −0.424) in patients with thrombosis." (PMID 40076681, 2025). "Furthermore, we found that either over-expressing tumour necrosis factor alpha (TNF-α) or blocking soluble TNF receptor (sTNF-R) could lead to a reduction of both of the organ dysfunction endpoints (Ang2 and Thrombosis)." (PMID 36261775, 2022). "LP-HFY05 and dipyridamole could down-regulate NF-κB p65, IL-6, TNF-α, and IFN-γ expression in renal tissues of mice with thrombosis, and the effects of LP-HFY05-H and dipyridamole were similar, and the effects of both were significantly better (P < 0.05) than those of LP-HFY05-L." (PMID 35308280, 2022). "Neutrophil extracellular traps (NETs), cytokine surges (e.g., IL-6, TNF-α), and brain-derived extracellular vesicles carrying procoagulant microparticles may converge on the pulmonary vasculature, creating a fertile ground for in situ thrombosis even in the absence of deep vein thrombosis (DVT)." (PMID 41149789, 2025).
amyotrophic lateral sclerosis (70 papers, 2012 to 2025). Amyotrophic lateral sclerosis (ALS) is a neurodegenerative disease characterized by progressive muscular paralysis reflecting degeneration of motor neurons in the primary motor cortex, corticospinal tracts, brainstem and spinal cord. "Reportedly, D2R agonists are shown to significantly reduce the activation of astrocytes and the release of TNF-α in the spinal cord of a mouse model of amyotrophic lateral sclerosis and also prevent motor neuron loss (or death)." (PMID 33430188, 2021). "In amyotrophic lateral sclerosis (ALS), a mechanism involving tumor necrosis factor-alpha (TNF-α) and the NF-κB pathway, has been shown to cause motor neuron necrosis, and there is also evidence that it causes damage to the blood–brain barrier (BBB)." (PMID 39766497, 2024). "In neuronal and glial cells, preclinical studies showed that MMP9 contributes to the motor neuron cell death in amyotrophic lateral sclerosis (ALS) patients by regulating TNF-α and CD95L expression." (PMID 36544756, 2022). "KEGG enrichment analysis indicated that DEGs were mainly involved in amyotrophic lateral sclerosis, the synaptic vesicle cycle, proximal tubule bicarbonate reclamation, glycine biosynthesis, and the TNF signaling pathway." (PMID 36205565, 2022). "Currently, thalidomide is under investigation to treat neurodegenerative disorders that implicate TNF-signaling such as AD, PD and amyotrophic lateral sclerosis (ALS) as this small-drug molecule can penetrate into the brain." (PMID 29751683, 2018). "Minocycline inhibits the expression of CD68, cell surface markers of M1 polarized microglia, and inflammatory cytokines (IL-1β and TNF-a) both in vitro and in an animal model of amyotrophic lateral sclerosis." (PMID 28790417, 2017). "High levels of TNF have been found in cerebrospinal fluid (CSF) and serum of patients and animal models of CNS pathologies, including cerebral stroke, trauma, Parkinson’s disease (PD), Alzheimer’s disease (AD), MS, and amyotrophic lateral sclerosis (ALS)." (PMID 32977412, 2020). "Treatment with violacein significantly decreased pro-inflammatory cytokines such as TNF-α, IL-1β, and IL-6 in the spinal cord of rats with amyotrophic lateral sclerosis (ALS)." (PMID 40430892, 2025). "With respect to amyotrophic lateral sclerosis (ALS), significantly higher blood levels of IL‐1β, IL‐6, IL‐8, TNF‐α, TNF receptor 1 (TNFR1), and vascular endothelial growth factor (VEGF) were found in the disease condition compared to the control group." (PMID 40709483, 2025). "This gene encodes a serine/threonine kinase that may play a role in the response to environmental stress and cytokines such as the tumor necrosis factor alpha and it's activation has been shown to mediated motor neurons degeneration in amyotrophic lateral sclerosis." (PMID 37347276, 2023). "Conditioned medium from bone marrow derived stem cells (BMSCs-CM) was reported to markedly reduce the expression of IL-6, iNOS and TNF-α in astrocytes cells derived from amyotrophic lateral sclerosis (ALS) transgenic mice." (PMID 31024252, 2019). "In a mouse model of amyotrophic lateral sclerosis (ALS), the progression of neurodegeneration is accompanied by elevation of TNFα mRNA transcripts and protein in the reactive microglia found in the spinal cord." (PMID 30401897, 2018). "When primary murine astrocytes were exposed to MCM collected from microglial models of Huntington’s disease (HD) and amyotrophic lateral sclerosis (ALS), they polarized to an A1-like phenotype and increased secretion of TNF-α and IL-1β." (PMID 36915214, 2023). "To illustrate, knockout of microglial-derived IL-1α, TNF-α, and C1q—pro-inflammatory astrocytic activators—in a genetic mouse model of amyotrophic lateral sclerosis (ALS) increased animal life span and improved peripheral nerve fiber formation when compared to control." (PMID 37238617, 2023).
amyotrophic lateral sclerosis (continued). "In a study analyzing amyotrophic lateral sclerosis (ALS) blood cells, which normally secrete TNF-α and IL-6, researchers found that these cells were toxic to rat neurons in vitro." (PMID 29167670, 2017). "In amyotrophic lateral sclerosis (ALS), both TNF-α and soluble TNF receptor levels are raised in serum of patients." (PMID 27075886, 2016). "MS: multiple sclerosis; ALS: amyotrophic lateral sclerosis; TDP-43: TAR DNA-binding protein 43; IL: interleukin; IGF: insulin growth factor; SOD: superoxide dismutase; NO: nitric oxide; TNF: tumour necrosis factor." (PMID 22269588, 2012). "This review summarizes the current knowledge of the cellular and molecular mechanisms by which TNF-α links the neuroinflammatory and excitotoxic processes that occur in several neurodegenerative diseases, but with a special emphasis on amyotrophic lateral sclerosis (ALS)." (PMID 24966471, 2014). "CASP3, CASP9, tumor necrosis factor (TNF), and Bcl-2 were shown to be major contributory genes in connection with flavonoid action, amyotrophic lateral sclerosis (ALS), the epithelial cell apoptotic process, and hypoxia." (PMID 37446564, 2023). "Moreover, significant induction of G-CSF, IL-2, IL-15, IL-17, MCP-1, MIP-1α, TNF-α, and VEGF levels has been observed in amyotrophic lateral sclerosis (ALS) patients." (PMID 36052093, 2022). "Furthermore, human mutations in (Cu/Zn) superoxide dismutase-1 (mSOD1) G93A and G85R, which cause non-cell-autonomous motor neuron death in amyotrophic lateral sclerosis (ALS), activate microglia and induce production of inflammatory mediators, including TNF-α, IL-1β, and NO." (PMID 23234315, 2012).